STAT1 (signal transducer and activator of transcription 1)
Diseases named in the same sentence as STAT1 in open-access papers (continued):
Sharing a sentence is not in itself a finding about the gene and the disease.
infection (continued). "Additional pro-inflammatory markers in the NHP liver dataset included enriched Klf6, Stat1 and Irf1, as well as Il23 in late-stage infection." (PMID 29724035, 2018). "After prolonged HEV gt3 infection for more than 3 months, significantly lower expression levels of STAT1, RSAD2 and MX1 compared to uninfected controls were observed, suggesting possible viral interference with the host’s cell innate immune signaling." (PMID 28811492, 2017). "SOCS1, encoding Suppressor of cytokine signaling 1, which is induced by STAT1 activation in response to cytokine stimulation, was induced early in infection (6 h), followed by an active downregulation from 6 to 16 h of infection." (PMID 28993767, 2017). "Real-time PCR analysis was performed to confirm the microarray results for Stat1, Stat2, Zfp456, Nt5c2, NfκB2 and Samd9l post V3000 and V3034 infections at various time points." (PMID 28446152, 2017). "After 20 days of infection STAT1KO mice that received WT monocytes showed two times more parasites in the spleen than control STAT1 KO mice." (PMID 29089636, 2017). "The impaired ability of type I IFN to block infection reflected viral antagonism of type I IFN-mediated phosphorylation of STAT1 and STAT2." (PMID 28152048, 2017). "This interaction occurs during infection to prevent transport of STAT1 to the nucleus in order to inhibit interferon signaling." (PMID 28812539, 2017). "Cells were then harvested after 2, 6, 12, and 24 h of infection, processed, and levels of phosphorylated STAT1 (pSTAT1) and viperin were analyzed by WB." (PMID 28769891, 2017). "The levels of representative ISG mRNAs, STAT1, ISG15, and viperin, peaked at around 9 h post infection and with the exception of STAT1 remained at high levels in infected cells." (PMID 28087593, 2017). "We found that phosphorylation of STAT1 in CSFV infected PK-15 cells was up-regulated at early stages of infection (24, 36, and 48 h p.i.), but slightly declined at later stages of infection (after 60 h p.i.)." (PMID 29312239, 2017). "Stat1 knock-out in the hematopoietic compartment rendered multiple peripheral cell-subsets permissive to viral replication early during the course of infection before peripheral clearance, presumably due to the rise in various pro-inflammatory cytokines." (PMID 28290449, 2017). "Infection alone increased the total levels of STAT1 and STAT2 protein, although notably less so at an MOI of 1 as compared to MOI 0.1." (PMID 28152048, 2017). "If the antiviral activity of CRT0066101 was acting by enhancing IFNAR signaling, one would expect to see enhanced STAT1 phosphorylation following HeLa cell infection in the presence of the drug." (PMID 28228588, 2017). "The restriction of TBFVs was linked to the intrinsic cellular response to infection, as it was dependent on signaling through both IFNAR1 and STAT1." (PMID 28650973, 2017). "Binding of the measles virus P protein to the SH2 domain of STAT1 limits an IFN response to infection." (PMID 28498306, 2017). "Real-time PCR analysis was performed to confirm the microarray results for randomly selected genes a) Stat1, b) Stat2, c) Zfp456, Nt5c2 and NfκB2 post V3000 infection and d) Samd9l post V3000 and V3034 infections." (PMID 28446152, 2017). "Since the activation and subsequent differentiation of iMOs depends in part on STAT1 mediated IFNγ signaling, it is essential that we understand the role of this immune cell subset during infection with L. donovani." (PMID 29089636, 2017). "We observed virtually identical fecal shedding of EW-RV in WT, Ifnlr1-/-, Ifnar1-/-, Ifnar1-/-Ifnlr1-/- or Stat1-/- mice during the first 7 days post infection (dpi)." (PMID 27128797, 2016). "In our study, the Vero cells and A549 cells were infected with NDV at a multiplicity of infection (MOI) of 3, and the STAT1 expression in infected cells was detected by Western blot at different time points post infection (p.i.)." (PMID 26859759, 2016).
infection (continued). "STAT1, 3, 5B and 6 had increased phosphorylation on day four post-infection, but all had a reduced phosphorylation 10–14 days post-infection." (PMID 27472318, 2016). "Stat1Y701F mice infected with L. monocytogenes were highly susceptible to infection when compared to WT, but showed reduced bacterial loads in lungs, brain, liver, and spleen 48 h and 72 h after infection compared to the Stat1−/− mice." (PMID 26882544, 2016). "JEV infection triggers antiviral Jak-STAT pathway by increasing the STAT1 phosphorylation in human microglial cells in early course of infection." (PMID 27282499, 2016). "Other than Le. pneumophila, STAT1‐independent type I IFN signaling is thought to partially rescue cells and organisms from infection with viruses causing STAT1 inhibition or degradation." (PMID 26882544, 2016). "We observed increased expression of Stat1 in the blood of infected Ifnar1-/- mice versus WT controls at day 1 post infection when bacterial loads were similar, suggesting a direct of role of type I IFN signaling." (PMID 26918359, 2016). "The essential role of Stat1 for the efficient clearance of MNV infections by the host immune system was shown earlier." (PMID 27294868, 2016). "This is in contrast to wild-type mice that have higher basal levels of antiviral ISGs, respond faster by production of IFN-β, and have a more robust STAT1-mediated expression of ISGs required to contain the infection." (PMID 26819220, 2016). "In a previous study we demonstrated that Mycobacterium avium infection induces Stat-1 hyperactivation for a considerable period and that it is important for macrophage survival after the establishment of an infection." (PMID 27437406, 2016). "Infection by ZJ1 of A549 cells led to obvious reduction of phospho-STAT1 with subsequent reduction of total STAT1 protein." (PMID 26859759, 2016). "Compared with the rHep-Flury infection group, the phosphorylation level of STAT1 in Hep-dG-infected cells was significantly increased." (PMID 26217322, 2015). "We recently found that infection with T. crassiceps or its excreted/secreted products are able to inhibit STAT1 phosphorylation in macrophages and splenocytes in response to IFN-γ." (PMID 26090422, 2015). "Such inhibition frequently occurs during infection by certain pathogens, which attack STAT1 in order to evade detection and control by the immune system." (PMID 26196960, 2015). "Among the interferon-stimulated proteins, two apoptosis-associated molecules (including NUB1 and STAT1) and two autophagy-associated proteins (including SQSTM1 and Irgm1) were significantly up-regulated only in the Hep-dG infection group." (PMID 26217322, 2015). "For example, while STAT1 signaling suppresses cell proliferation during hematopoiesis, IFN-γ-induced STAT1 signaling can also drive hematopoietic stem cells to enter the cell cycle and proliferate to replace leukocytes lost during infection." (PMID 26196739, 2015). "Surprisingly, expression of STAT1 only modestly inhibited EBOV GP/rVSV infection, likely because significant levels of STAT1 are constitutively expressed within these cells and control of STAT1 activity is primarily regulated by its phosphorylation status." (PMID 26562011, 2015). "On day 4 post-infection, a 90% reduction in Setdb2 transcript was observed in CD11b+ cells from Stat1-/- lungs relative to control lungs." (PMID 26709698, 2015). "Nod1 (C10) and its responsive genes Irf7 and Stat1 (C11) were elevated late during infection as well as interferon-induced genes Cxcl10, Ifit1-3, Iigp1 and Rsad2 (C7)." (PMID 26367386, 2015). "In STAT-1 mice, the route of infection is critical as only the i.p route produced 100% lethality by day 8, the s.c. route resulting in ~60% lethality, and lesser still the i.n. route causing ~30% lethality." (PMID 26266264, 2015). "The phosphorylation of STAT1 was notably reduced in CD4+ T cells in the FeD mice on day 7 post-infection." (PMID 25768944, 2015).
infection (continued). "HCV did not apparently affect the phosphorylation of STAT1 and STAT2 at 24 hours post-infection, but it slightly increased the STAT1 phosphorylation at 48 hours post-infection, in agreement with its modest effect on ISRE." (PMID 26023919, 2015). "Recently, it has been demonstrated that influenza virus-induced SOCS1 inhibits the phosphorylation of STAT1 at early stages of infection." (PMID 26206138, 2015). "As expected, 100% of Stat1fl/fl mice survived infection with Δγ34.5, but 100% of Stat1N-/- mice infected with Δγ34.5 died, demonstrating that neural STAT1 deletion restores virulence to Δγ34.5." (PMID 26153886, 2015). "STAT1 dimerization allows for nuclear import and subsequent DNA binding to induce transcription, and immunofluorescence revealed that STAT1 translocation to the nucleus is unaffected by infection." (PMID 26196739, 2015). "In a previous experiment using the same dose and infection route, STAT1 expression was found to be maximal 6 days after infection in the kidney tissue." (PMID 26397117, 2015). "As a testament to the importance of IFN-γ and STAT1 signaling in the control of infections, many pathogens have evolved mechanisms to directly inhibit pathway components." (PMID 26196739, 2015). "Western blot analysis revealed that LV-shDUSP1 infection enhances phosphorylation of STAT1 compared to LV-cont-infected cells (P = 0.06)." (PMID 25798824, 2015). "Similar to the results from the Western blot experiments, infection with T. cruzi alone induced STAT1 activation as demonstrated by binding to high-affinity GAS elements and, in addition, this binding activity correlated positively with parasite burden." (PMID 25340519, 2014). "Our experiments demonstrated that IAV-provoked STAT1 phosphorylation at the early stage of infection was inhibited by the virus-induced SOCS-1." (PMID 24391501, 2014). "It would be of interest in the future to perform microarray studies in infected BMDC in the presence and absence of STAT1 to determine what role, if any, Toxoplasma-activated STAT1 plays in the host response to infection." (PMID 23527309, 2013). "Adult mice in which IFNγ expression or its signalling are affected such as IFNγ−/− or STAT-1−/− mice display high sensitivity to the infection and long-term carriage of the parasite." (PMID 24367259, 2013). "MERS-CoV infection did not prevent the IFN-induced nuclear translocation of phosphorylated STAT1, in contrast to infection with SARS-CoV where this block inhibits the expression of antiviral genes." (PMID 23620378, 2013). "In the mock and non-misfolding B27E45M-transfected cells the phosphorylation of STAT-1 serine 727 is significantly decreased as a result of the PKR inhibition 2 hours after infection." (PMID 23349666, 2013). "During the third phase from day 5 until day 15 post-infection, transcriptional regulators STAT1 and STAT3 are highly expressed, together with IFNγ characteristic of CD4 T-lymphocyte activity." (PMID 23687968, 2013). "In our previous study we observed that LPS- and S. enteritidis-induced phosphorylation of STAT-1 serine 727 tends to be slightly stronger in HLA-B27-expressing cells right after LPS exposure or infection when compared to control cells." (PMID 23349666, 2013). "We were unable to achieve the high levels of infection (>90%) required for looking at total STAT1/STAT2 phosphorylation in infected cells with any virus except RPV-Sa." (PMID 23431397, 2013). "WT mice which received Stat1−/− bone marrow responded to infection with a systemic cytokine storm, i.e elevated serum levels of almost all measured cytokines and chemokines (IL6, IL22, TNFα, MCP1, IL10, Rantes, IP10 and MCP3)." (PMID 22719255, 2012). "Stat1-deficient mice succumb to Lm during the early, innate phase of infection, strongly suggesting a dominant role for Stat1 in IFNγ-mediated macrophage activation." (PMID 22719255, 2012).
infection (continued). "To further show that secretion of IFNγ is impaired in CD4+ T cells during infection, we measured STAT1 phosphorylation in dLN CD4+ T cells of L. major-infected N1N2ΔCD4Cre mice." (PMID 22396647, 2012). "Whole cell lysates were prepared at 48 h post-infection and subjected to Western blot analysis using antibodies against STAT1, phospho-STAT1 (Tyr701), MxA, and actin." (PMID 23139774, 2012). "Our data highlight the importance of and requirement for IFNγ-activated macrophages for clearance of the pathogen during early phases of infection, and show a yet unanticipated detrimental role for T cell Stat1." (PMID 22719255, 2012). "In comparison to the delNS1 viruses, the IGR-39 cell interferon response was reduced after infection with wildtype NS1 expressing IVR-116 virus as indicated by decreased levels of phosphorylated STAT1 and STAT2 and alleviated MxA expression." (PMID 22563505, 2012). "Pre-mRNAs transcribed from the IL6, IFIT2 and STAT1 genes were present in mock-infected cells, and decreased significantly in concentration following infection with AdEasyE1, whereas only minimal differences in GAPDH mRNA were detected." (PMID 22912576, 2012). "To further study the contribution of individual immunecompetent cells for the innate phase of Lm infection we analysed resistance to lethal infection and bacterial clearance after tissue-restricted Stat1 ablation." (PMID 22719255, 2012). "T cell-specific Stat1 ablation lead to a decrease in Rantes levels at day two after infection, at day three the amount of the tested chemokines reached WT level." (PMID 22719255, 2012). "Spleens and livers of infected animals with conditional Stat1 gene ablation were analysed using H&E staining to determine the severity of inflammation two days post-infection." (PMID 22719255, 2012). "Mice with T cell-restricted Stat1 gene deletion showed smaller infiltrate areas compared to the WT, again reflecting the protection of these mice from infection." (PMID 22719255, 2012). "One previous report used two different luciferase reporters to demonstrate that infection with Toxoplasma inhibits STAT1 transcriptional activity." (PMID 23240025, 2012). "DNA from S221-infected wild type, STAT1−/− and STAT1−/−/2−/− BMMs was harvested at 12 and 24 hours post-infection, and quantitative PCR was performed on anti-STAT2 precipitated DNA using primer pairs specific to ISREs located in the promoters of these genes." (PMID 21379341, 2011). "Several groups have observed differences in antibody and CD8+ T cell responses in IFNAR-/- and STAT1-/- mice after infection or vaccination." (PMID 22144897, 2011). "In fact, infection with any of these viruses led to decreased STAT-1 phosphorylation compared to mock-infected cells." (PMID 22096477, 2011). "Serum IFN-α levels in STAT1−/−/2−/− mice followed the same kinetics as STAT1−/− mice, including increased expression at 18 hours post-infection." (PMID 21379341, 2011). "Infection of STAT-1 knockout mice with ~1,000 pfu of MACV via the intraperitoneal route resulted in lethality (defined by either death, or euthanasia of moribund mice) in 6/6 mice (mean time to death (MTD) 7.3 ± 0.5)." (PMID 21672221, 2011). "Although each single-deficient mouse strain possessed similar levels of viral RNA as STAT1−/−/2−/− mice at 12 and 18 hours post-infection, the levels of virus in the serum and spleen were 6–7 fold higher in STAT1−/− mice than STAT2−/− mice by 24 hours." (PMID 21379341, 2011). "Infection with either WNV or DENV inhibits IFN-mediated STAT1 activation in vitro, including primary human DC cultures." (PMID 21379341, 2011). "In fact, there was down-regulation of genes involved in innate immune response like IL2, IL15 and STAT1 at early stages (4 and 8 hpi) of infection." (PMID 21439068, 2011).
infection (continued). "Infection of STAT1-/- mice with either 104 or 103 TCID50 of WT-v or M1v demonstrated that MNV-1 lacking VF1 was partially attenuated in this system exhibiting delayed replication kinetics in the murine host." (PMID 22174679, 2011). "Serial sampling studies (days 0, 3, 5, and 7 post-infection) were performed to investigate the pathogenesis of MACV lethal infection in STAT-1 knockout mice." (PMID 21672221, 2011). "This claim is supported by the viral load data, where tissue viral burden in STAT2−/− mice remained slightly lower than their STAT1−/− counterparts at multiple timepoints following infection." (PMID 21379341, 2011). "This increased upregulation in STAT1−/− mice at 24 hours is consistent with the elevated levels of type I IFN observed at 24 hours post-infection." (PMID 21379341, 2011). "JEV and Kunjin virus (a subtype of WNV) infection blocks IFN-α-induced phosphorylation of both STAT1 and STAT2 in multiple cell lines." (PMID 21379341, 2011). "Overall, there are important similarities and differences in the disease course of these models, and further work must be done to directly compare changes in STAT-1 knockout mice to NHP models or human infections." (PMID 21672221, 2011). "It is well established that MNV is sensitive to an effective innate immune response: type I and II interferon are known to inhibit viral translation, a fact supported by the observed sensitivity of STAT1-/- mice to infection." (PMID 22174679, 2011). "STAT2 binding to the Oas1a promoter in STAT1−/− cells was only significantly enriched at 24 hours post-infection, while Oas1b and IRF7 had significant enrichment at both time points." (PMID 21379341, 2011). "Serum levels of IFN-α and IFN-β in wild type, STAT1−/−, STAT2−/−, and STAT1−/−/2−/− mice were measured by ELISA between 0 and 24 hours post-infection." (PMID 21379341, 2011). "Conversely, both STAT1 and STAT2 single-deficient mice survived infection with DENV at this same dose of virus, suggesting there are sufficient compensatory mechanisms that protect against DENV infection in the absence of either one of these STAT proteins." (PMID 21379341, 2011). "The intraperitoneal route of infection of STAT-1 knockout mice with MACV resulted in a much more rapid and lethal disease course compared to subcutaneous or intranasal routes." (PMID 21672221, 2011). "Subcutaneous infection of STAT-1 knockout mice resulted in death in 4 of 6 mice, with a delayed time-to-death (MTD 10.5 ± 1.3), while intranasal infection was lethal in only 1 of 4 mice (death on day 20)." (PMID 21672221, 2011). "The infection of AGS cells in the presence of siRNA specific for NOD1 resulted in the impaired nuclear translocation of Stat1 and production of IFN-β and IP-10, but unchanged nuclear translocation of NF-κB subunit, p65." (PMID 21152124, 2010). "We observed marked differences in pathology of lungs from 129 WT mice compared to STAT1−/− mice after infection with the rMA15 virus." (PMID 20386712, 2010). "In situ hybridization was performed on lungs from 129 WT, IFNAR1−/−, IFNGR−/− and STAT1−/− mice harvested at days 2, 5, and 9 post-infection." (PMID 20386712, 2010). "Urbani virus infected STAT1−/− mice also showed increased and sustained virus replication in the lungs as late as 15 days post-infection while virus was detectable only through day 5 post-infection in the 129 WT mice." (PMID 20386712, 2010). "Antiviral effects of type I IFNs were not obvious, probably due to the fact that SARS-CoV infected cells inhibit STAT-1 signalling and viral replication peaks early after infection when treatment with pegylated IFN-α started." (PMID 20140198, 2010). "By day 5 post-infection, lung lesions were more severe in STAT1−/− mice, consistent with persistently high virus titers." (PMID 20386712, 2010).